IL6 (interleukin 6)
Diseases named in the same sentence as IL6 in open-access papers (continued):
Sharing a sentence is not in itself a finding about the gene and the disease.
tumor (continued). "In tumor cells, interleukin-6 (IL-6) signaling can lead to activation of the epidermal growth factor receptor (EGFR), which prolongs Stat3 activation." (PMID 39000275, 2024). "Using transcriptomic profiling, bioinformatic analyses, and structural modeling, we found that E2F1 orchestrates the tumor niche by activating an IL6-based gene regulatory network (GRN) and a highly inflammatory secretome." (PMID 39544930, 2024). "IL6 is a multifunctional cytokine that plays an important role in a wide range of biological processes in various cell types, including tumor cells." (PMID 38727303, 2024). "The levels of nitrotyrosine, 8-OHdG, and IL-6 were significantly higher in the venous blood of CRC patients than in healthy volunteers, with a positive correlation between IL-6 and the histological type of the tumor." (PMID 39337548, 2024). "IL-1β and IL-6 are highly expressed within the tumor microenvironment (TME) and play well-established roles in PDAC development and progression." (PMID 39260693, 2024). "We review the intricate mechanisms by which IL6 influences tumor initiation, growth, metastasis, and resistance to therapy." (PMID 39766086, 2024). "Studies have illuminated the significant functions of key interleukins, including IL-6, IL-8, IL-1β, and IL-11, in promoting tumor growth, osteoclast development, and metastasis colonization in the skeletal system." (PMID 39125732, 2024). "IL-6 contributes to tumor promotion by the expansion and survival of malignant cells, neo‐angiogenesis, and inflammation, and it promotes expression of the T helper Th2 associated with IL-4." (PMID 38443899, 2024). "Pro-inflammatory interleukins, including IL-1 and IL-6, exhibit a propensity towards fostering osteoclastogenesis and tumor proliferation." (PMID 39125732, 2024). "The anti-tumor defense mediated by natural killer cells (NK) is also activated by IL-6 expression modulation." (PMID 38473864, 2024). "Cytokines expressed by tumor cells or endothelial cells in the tumor microenvironment, such as GM-CSF and IL-6, can promote MDSC induction to suppress antitumor IFN-γ+ T cell production and increase angiogenesis in the mouse HCC microenvironment." (PMID 38397901, 2024). "CAR-T cells effectively eliminate tumor cells through the release of perforin, granzymes, and cytokines, such as IL-1, IL-6, IL-15, interferon-gamma (IFN-γ), and GM-CSF." (PMID 38550613, 2024). "Overexpression of IL-6 is known to correlate with disease severity and tumor growth in MM (Harmer, Falank & Reagan, 2019)." (PMID 39619207, 2024). "DCs, macrophages, and neutrophils exert their tumor cell-killing activity by releasing cytokines such as TNFα, IL-6, and IFNγ." (PMID 39204319, 2024). "According to the results of the literature review, we included the previously reported independent variables of high risk, such as IL-6, IL-10, LDH, KL-6, smoking history and suspension of anti-tumor therapy into the multivariate regression analysis." (PMID 38983925, 2024). "Direct proliferative effects of IL-6 on peritoneal metastatic cells have been documented in several tumor types relevant to PC, both in cell lines and in murine models." (PMID 38689325, 2024). "BIRB-796 also inhibits IL-6 secretion induced in BMSCs through adherence to MM cells, thereby inhibiting tumor cell proliferation." (PMID 38254747, 2024). "In line with our in vitro data, we detected a strong increase of Il6 expression in tumor versus healthy tdTomatopos EGCs." (PMID 39030280, 2024). "An interesting study conducted on renal carcinoma cells demonstrated how tumor cells can influence the development of CD34+ progenitor cells into mature DCs through the production of IL-6 and CSF-1, which in turn bind to the CSF-1R." (PMID 39457693, 2024). "The relationship between IL-6 and inferior cancer-related outcomes in this diverse, pan-tumor cohort are congruent with prior retrospective analyses of interventional clinical trials and observational studies from single tumor types." (PMID 39403935, 2024).
tumor (continued). "In BC, IL-6 has been shown to promote tumor growth, invasion, and metastasis through multiple mechanisms." (PMID 38338683, 2024). "We also analyzed the expression of other Th2 cytokines besides TGFβ-1 (IL-4 and IL-6) in spleen and tumor samples, but treatment with mHAdLyp.sT didn’t lead to any significant changes when compared to the buffer group (data not shown)." (PMID 38267626, 2024). "It activates key signaling pathways such as PI3K/Akt and NF-κB and stimulates proinflammatory cytokines like TNF-α and IL-6, facilitating tumor growth, angiogenesis, and metastasis." (PMID 39184804, 2024). "Studies have shown that IDO1 fosters tumor cell neovascularization by elevating IL-6 levels, counteracting the anti-cancer effects of the inflammatory cytokine IFN-γ, thereby promoting cancer progression." (PMID 38883986, 2024). "In cancer, cell migration, which is vital for tumor metastasis, is regulated though chemokines, cytokines, and growth factors, for which the IL-6 pathway is one of the regulators." (PMID 38612423, 2024). "This study aimed to investigate IL6 and IL6R expression in a large cohort of retrospectively collected patient tumour specimens and determine association with clinical outcomes and characteristics." (PMID 39766336, 2024). "Mean serum IL-6 levels also showed a similar trend, with values of 31.60 pg/ml for WDSCC, 64.00 pg/ml for MDSCC, and 94.12 pg/ml for PDSCC, suggesting a role for IL-6 in the progression and invasion of tumor disease." (PMID 38803729, 2024). "Recent evidence underscores that elevated IL-6 levels contribute to the establishment of an immunosuppressive tumor microenvironment and are indicative of poor prognosis and resistance to ICIs." (PMID 39335733, 2024). "IL-6, as a pro-inflammatory cytokine, is released by various cells, including cancer cells, playing a pivotal role in tumor cell expansion and differentiation." (PMID 39738201, 2024). "It was obvious that the IL-6 SNP had a high connotation with tumor sizes in NSCLC patients over the allelic (p = 0.05) and dominant models (p = 0.036)." (PMID 38103126, 2024). "On the other hand, the continuous secretion of IL-1, IL-6, and IL-8, typical of a persistent inflammatory state, eventually results in effective immunosuppression and tumor escape." (PMID 39766202, 2024). "This, in turn, promotes the production of pro-inflammatory factors such as IL-6, thereby exerting a significant anti-tumor effect." (PMID 38675217, 2024). "iCAFs, with low α-SMA and high IL-6 levels and inflammatory features, are located farther away from tumor cells and activated by paracrine factors secreted from tumor cells." (PMID 39195299, 2024). "Bone marrow-derived macrophages play an important role in the tumor microenvironment by secreting various cytokines, such as IL-6 and IL-4, thereby regulating the growth, invasion and migration of tumor cells." (PMID 38261741, 2024). "MDSCs can also promote tumor metastasis by enhancing β-adrenergic signaling and the IL-6/STAT3 pathway." (PMID 38464516, 2024). "Since IL-6 acts through a positive feedback mechanism, it modulates IL-6 toward a pro-tumor effect-generating cytokine." (PMID 38279220, 2024). "On the other hand, the WDR5/MLL1-H3K4me3 axis regulates the expression of cytokines in the tumor microenvironment, such as TGFβ, TNFα1, and IL6." (PMID 39201460, 2024). "The transcription factor signal transducer and activator of transcription factor 3 (STAT3) plays a fundamental role in mediating the tumor-promoting effect of IL-6, and the IL-6/STAT3 trans-signaling pathway is a key regulator of tumor differentiation." (PMID 39911672, 2024). "Of note, secretion of IL-6 and IL-8 is a key characteristic of senescent cells and an integral component of SASP linked to chronic inflammation and tumor promotion." (PMID 38900577, 2024). "In another study, fibroblasts derived from PitNETs with cavernous sinus invasion were found to increase tumor cell migration and invasion through the secretion of IL-6." (PMID 38716256, 2024).
tumor (continued). "IL6 is a pro-inflammatory cytokine that has a vital role in tumour progression through growth-promotion, anti-apoptotic activity, and modulation of the immune response." (PMID 39613865, 2024). "The factors IL-6 and IL-8 secreted by senescent cells promote angiogenesis and tumor vascularization, promoting BRCA tumor cell invasion." (PMID 38358910, 2024). "Tumor cells release factors that either directly (e.g., IL-8) or indirectly (e.g., parathyroid hormone-related peptide: PTHrP, IL-6) stimulate bone resorption." (PMID 39596154, 2024). "IL-6 promotes tumor growth and metastasis through several mechanisms, including inflammation, angiogenesis, epithelial-mesenchymal transition (EMT), and metabolic reprograming." (PMID 38482486, 2024). "T-regulatory cells and myeloid-derived suppressor cells are both simultaneously upregulated by IL-6, which boosts IL-6 production resulting in a diminished immune response to the tumor." (PMID 38803729, 2024). "MDSCs produce IL-6, and the diminishing levels of Gr-1+ cells likely reduce tumor promotion, in part through the reduction of IL-6 levels." (PMID 39338937, 2024). "The M1 macrophage exert a proinflammatory effect and secrete cytokines, like IL-6 and IL-12, to inhibit tumor growth through phagocytosis, proinflammatory response, and activation of immune response." (PMID 38167452, 2024). "By blocking IL-6 as the main downstream effector, cell proliferation and tumor growth was reversed in vivo." (PMID 39020414, 2024). "This persistent inflammatory state in the TME contributes to tumor-supportive processes, including angiogenesis, invasion, and metastasis, which are often mediated by cytokines such as IL-6, TNF-α, and chemokines like CXCL8." (PMID 39769051, 2024). "These transcription factors lead to the secretion of pro-inflammatory cytokines, including TNF-α, IL-1β, and IL-6, which further promote tumor growth." (PMID 39267826, 2024). "The relation between inflammation and cancer was described in previous studies, Interleukin-6 (IL-6), which is a cytokine that is involved in immune responses and inflammation and is known to be overexpressed in all tumor types." (PMID 38072891, 2024). "In cardiac myxoma, miR-217 acts as a tumor suppressor by negatively regulating the oncogenic IL-6 gene." (PMID 38826780, 2024). "TAMs are drawn to the cancer site by chemokines like C-C motif chemokine ligand 2 (CCL2), and aid tumor development and invasion by secreting cytokines and growth factors including interleukin-6 (IL-6), TGF-β, and VEGF." (PMID 38523646, 2024). "Gene expressions for tumor promoting genes such as Arg1, Il6, Il10, Mmp9, Lgals9, and Vegfa were significantly decreased, whereas that of the tumor suppressive gene such as Il12 increased." (PMID 39702544, 2024). "Blocking IL-6 pathway can prevent this progression through the inhibition of tumor migration and invasion." (PMID 38726321, 2024). "Comprehensive gene expression analysis of tumor localization showed increased expression of genes related to oxidoreductase and lipid metabolism in the primary tissues of the group with high serum IL-6 levels." (PMID 38510850, 2024). "Once activated, APCs intensify the inflammatory milieu by secreting cytokines like IL-6, potentially enhancing T-cell infiltration into the tumor and thus bolstering the adaptive immune response." (PMID 38217037, 2024). "Further, IL-6 was found in the tumor microenvironment of Kaposi’s sarcoma (KS) and the peripheral circulation of individuals with KSHV-associated tumors." (PMID 38534385, 2024). "NF-κB regulates pro-inflammatory cytokines such as TNF-α, IL-1β, and IL-6, which contribute to tumor progression and metastasis." (PMID 39861671, 2024). "Survival analysis revealed that cancer patients with higher IL-6 expression had a worse prognosis, pointing to the strong relevance of IL-6 signaling with tumor growth." (PMID 38274367, 2024).
tumor (continued). "In this study, we intend to comprehensively define the diagnostic value of individual and combined detection of serum IL-6 related to the traditional tumor markers carcinoembryonic antigen (CEA) and cytokeratin 19 fragment (CYFRA21-1) for AIS." (PMID 38529301, 2024). "IL-6 expression in tumor tissues was significantly correlated with TLG (p = 0.028) and uniformity (p = 0.029), and showed borderline significant correlations with maximum SUV, MTV, mean SUV, median SUV, spleen SUV, and SLR (p < 0.10)." (PMID 38627864, 2024). "Inactivation of IL-6 in somatotrophic senescent cells transforms them into strongly tumorigenic in NOD/SCID mice, while re-expression of IL-6 restores senescence control of tumor growth." (PMID 39012326, 2024). "Many studies have focused on the role of cytokines and cytokine receptors as potential targets for tumor intervention, including the inhibition of the tumor-promoting functions of IL-1β, IL-6, and TNF." (PMID 38317842, 2024). "In the context of cancer, IL6 can be produced by tumour cells and other populations in the tumour microenvironment (TME), including macrophages and inflammatory cancer-associated fibroblasts." (PMID 39766336, 2024). "Exercise leads to a 60% reduction in tumor incidence and growth in tumor-bearing mice and increased epinephrine and IL-6 by exercise are responsible for NK cell mobilization and redistribution." (PMID 39125923, 2024). "X-ray findings exhibited inhibited tumor growth and bone erosion in mice bearing knockdown IL-6 tumors." (PMID 38993553, 2024). "For example, exercise has been shown to increase the natural killer cell infiltration to the tumor site via exercise-induced epinephrine and IL6 secretion." (PMID 38725573, 2024). "The splenocytes of L. braziliensis-treated mice released higher amounts of IL-1β and IL-6 than the PBS control group at day 21 post tumor implantation." (PMID 38457336, 2024). "To further validate the expression of IL-6 in tumor EGCs, we performed fluorescence-activated cell sorting of enteric glia from healthy or tumor colonic mucosa of AOM/DSS-treated GFAPCreAi14fl/fl mice." (PMID 39030280, 2024). "There are two faces of IL-6 in tumor microenvironment: on one hand, IL-6 has been widely described as anti-inflammatory in some settings; on the other hand, it also plays critical roles in promoting inflammation and immunity." (PMID 38881895, 2024). "Here, we found that VDUP1 deficiency significantly increased the mRNA levels of IL-6 and TNF-α in the tumor tissues of AOM/DSS-treated mice compared to those in the tumor tissues of WT mice." (PMID 39272794, 2024). "We concluded that the U2932 and VAL cell-derived human IL6-expressing mouse models reproduced the clinical features of an aggressive DLBCL with a highly consistent pattern of tumor development." (PMID 39272864, 2024). "Numerous studies suggest that IL-6 can promote tumor invasion, inhibit tumor cell death, and facilitate tumor cell immune evasion through various mechanisms." (PMID 38800384, 2024). "IL-6 is a central molecule in tumor-related inflammation, and its downstream STAT3 signaling pathway is considered a key driver of cancer-associated inflammation." (PMID 39766882, 2024).
tumor (continued). "For example, several cytokines and chemokines generally considered to be predominantly toxic or immunosuppressive (IL-6, IL-8 and IL-10) have been shown to stimulate anti-tumor immune responses in certain settings." (PMID 39606250, 2024). "In GBM, RORα reduced tumour-promoting inflammation by downregulation of the JAK2 (Janus Kinase 2)/STAT3 (Signal Transducer And Activator Of Transcription 3) /IL-6 (Interleukin 6) and the TNF-α/NF-κB pathway." (PMID 38378853, 2024). "Further analysis of the IL6 expression levels in various cell types in the tumor microenvironment revealed a widespread expression in the myeloid and stromal cells." (PMID 39872866, 2024). "IL-1-activated CRC EGCs via IL-6, in turn, directly promote the differentiation of tumor-infiltrating monocytes towards SPP1+ TAMs." (PMID 39030280, 2024). "A prior investigation showed that the overexpression of CXCL1 and CXCL2 by interleukin 6 can enhance the recruitment of monocytes and drive macrophages towards a protumor phenotype, ultimately leading to the formation of a suppressive tumor microenvironment." (PMID 38214842, 2024). "Patients with tumor, or high IL-6 or elevated IL-10 expression exhibited a significantly shorter survival time." (PMID 38173531, 2024). "Subsequently, activated fibroblasts secrete interleukin 6 (IL-6), which participates in the communication between stromal cells and cancer cells in the tumor microenvironment." (PMID 38540273, 2024). "Previous studies have examined the correlation between tumor-derived IL-6 and β3-AR activation, as well as cancer cachexia-induced adipose tissue browning in mice genetically engineered to develop cancer cachexia." (PMID 38334644, 2024). "This runs in parallel with an impressive increase in IL-6 concentration in the peripheral blood serum, depending on IL-6 hyper-production by tumor T-cells from double mutant mice." (PMID 39337370, 2024). "IL-6 exerts its effects through IL-6R expressed on tumor cells and GAMs, promoting immunosuppressive GAMs and impairing T cell functions." (PMID 38994360, 2024). "IL-6 plays diverse roles in inflammatory and immune responses as well as in promoting cell survival and proliferation in both normal and tumor cells." (PMID 39451730, 2024). "On the other hand, il-6 deletion in tumor-bearing mice promotes the anti-tumor activities of effector T cells and inhibits tumorigenesis in vivo." (PMID 39281678, 2024). "Treatment of tumor bearing mice with WFA resulted in a significant decrease (p < 0.001) in IL-6 levels matching levels observed in tumor-free mice." (PMID 39394174, 2024). "We further extend this finding by elucidating the functional role of migratory tumor cells as a key modulator of different types of CAFs: IL6+ iCAF, CXCL12+ iCAF and myCAF." (PMID 38892065, 2024). "LPS can stimulate tumor cell progression by activating Toll-like receptor 4 (TLR4) through IL-6, which can subsequently induce phosphatidylinositol-3 kinase (PI3K) activation and epithelial–mesenchymal transition (EMT)." (PMID 39497925, 2024). "For example, COPS5, a c-Jun activation domain-binding protein-1, interacts with multiple tumor-related genes, including PD-L1, and involves many cell signaling pathways, such as IL6-Stat3 Signaling, TGF-β Signaling, and NF-κB Signaling." (PMID 38667328, 2024). "Il-6 recruits immune cells to the tumor microenvironment, which in turn promotes the secretion of more pro-inflammatory cytokines." (PMID 39990858, 2024). "Considering IL-6’s established role in tumor progression, these variations suggest an intensified pro-tumorogenic environment in OC patients preoperatively." (PMID 39000195, 2024). "In a particular study, the suppression of MUC2, the primary component of intestinal mucus, resulted in the phosphorylation of STAT3 in tumor cells via the cytokine IL-6." (PMID 38709264, 2024).